CIC (capicua transcriptional repressor)
Description:
Transcriptional repressor which plays a role in development of the central nervous system (CNS). In concert with ATXN1 and ATXN1L, involved in brain development.
Synonyms: KIAA0306; MRD45
Tractability: PROTAC: its protein half-life has been measured.
Gene: Protein-coding gene on chromosome 19 (42,268,537 to 42,295,801, forward strand). Ensembl gene ENSG00000079432.
Subcellular location: Nucleus
Subcellular location (Human Protein Atlas): Nucleoplasm; Vesicles
Gene Ontology:
Molecular function: protein binding; DNA-binding transcription factor activity, RNA polymerase II-specific; RNA polymerase II transcription regulatory region sequence-specific DNA binding; chromatin binding
Biological process: brain development; learning; memory; negative regulation of DNA-templated transcription; regulation of transcription by RNA polymerase II; social behavior
Cellular component: nucleoplasm; chromatin; nucleus; protein-containing complex
Genetic constraint (gnomAD): Loss-of-function variants: 20 observed, 116.67 expected, observed/expected ratio (o/e) 0.17, 90% interval 0.12 to 0.25. The upper end of that interval is the gene's LOEUF score, 0.25, which puts it in group 1 of 6, group 1 being the genes least tolerant of losing a copy. Missense variants: 1,979 observed, 2,188.4 expected, observed/expected ratio (o/e) 0.9, 90% interval 0.87 to 0.94. Synonymous variants: 1,070 observed, 940.06 expected, observed/expected ratio (o/e) 1.14, 90% interval 1.08 to 1.2.
Gene-disease validity (ClinGen):
ClinGen rates the evidence that CIC causes each of these diseases.
complex neurodevelopmental disorder (autosomal dominant): Definitive. A disorder that involves more than one phenotype associated with the central nervous system, including but not limited to intellectual disability, autism, and seizures (epilepsy).
Cancer hallmarks: invasion and metastasis (suppresses); change of cellular energetics (promotes); suppression of growth (promotes)
Homologues: Orthologues: chimpanzee CIC (99% identical), macaque CIC (99% identical), dog CIC (95% identical), pig CIC (94% identical), guinea pig CIC (94% identical), rat Cic (93% identical), mouse Cic (92% identical), rabbit CIC (61% identical), tropical clawed frog cic (50% identical), zebrafish cicb (39% identical), zebrafish cica (37% identical), Drosophila melanogaster cic (20% identical), and 1 more. Paralogues in human: BBX (6% identical).
Diseases named in the same sentence as CIC in open-access papers:
CIC is named in the same sentence as 85 diseases in open-access papers, as found by Europe PMC text mining. Sharing a sentence is not in itself a finding about the gene and the disease. The quoted sentences say what the papers report.
oligodendroglioma (59 papers, 2012 to 2025). A well-differentiated (WHO grade II), diffusely infiltrating neuroglial tumor, typically located in the cerebral hemispheres. "Most CIC mutations occur in the 1p/19q co-deletion, associated with a worse prognosis, but when disregarding the co-deletion cases, CIC mutations in astrocytoma and oligodendroglioma were 2%." (PMID 40564017, 2025). "Chromosome 19q13.2 has somatic mutations, comprising insertions/deletions encompassing the CIC gene, which has been validated by deep sequencing in recurrent oligodendrogliomas." (PMID 40564017, 2025). "IDH-mutant astrocytomas with 19q13 have also been reported before, but the authors have suggested that the underlying cause is the loss of the CIC gene, which resulted in oligodendroglioma like appearance." (PMID 38877600, 2024). "CIC mutations are rare in astrocytomas but have a higher likelihood of occurring in oligodendrogliomas and are linked to a lower malignant degree, according to radiomics and radiogenomics analysis conducted by Zhang’s laboratory." (PMID 38066643, 2023). "CIC mutations occur far more frequently in oligodendroglioma (52.1%) than in low-grade astrocytoma or glioblastoma." (PMID 37291277, 2023). "CIC, a transcriptional repressor, shows high number of mutations and copy number loss in oligodendrogliomas." (PMID 36711972, 2023). "CIC:p.R215W mutation is a common mutation in oligodendroglioma, which leads to the loss of CIC protein function, while we observed CIC:p.K1517del was the most frequent mutation in our group." (PMID 37533228, 2023). "In oligodendroglioma, patients with CIC mutations survived a median 3751 days, while CIC wild-type patients had a median survival of 1911 days." (PMID 37291277, 2023). "The CIC mutation was previously reported in an oligodendroglioma, knowing that CIC mutations are found in glioblastomas too." (PMID 36520193, 2023). "Up to 70% of oligodendrogliomas harbor recurrent mutations in the gene of capicua transcriptional repressor (CIC)." (PMID 36303101, 2022). "Oligodendrogliomas were characterized by a common 1p/19q deletion and mutations in CIC, FUBP1, Notch1, and TERT promoters." (PMID 35572524, 2022). "This is probably seen because CIC mutations occur primarily in grade 2 gliomas and oligodendrogliomas." (PMID 32676453, 2020). "Oligodendrogliomas often feature mutations in the Drosophila homolog of capicua transcriptional repressor (CIC) gene and the TERT promoter, which encodes for the catalytic subunit of telomerase." (PMID 31968687, 2020). "FUBP1 and CIC were both mutated in only 12% (2/17) of oligodendrogliomas examined, and all had sustained a variant in IDH1." (PMID 31217899, 2019). "The Capicua transcriptional repressor (CIC) gene is often mutated in oligodendroglial tumours with the codeletion of 1p and 19q." (PMID 31215432, 2019). "In the present study, we constructed three models for the preoperative prediction of CIC mutation statuses in oligodendroglial tumours." (PMID 31215432, 2019). "CIC mutations were found to be highly associated with oligodendroglioma histology, 1p/19q deletion, and IDH1/2 mutation." (PMID 30279357, 2018).
oligodendroglioma (continued). "The percentage of oligodendrogliomas with CIC mutations is in the range of 50 to 80%, whereas FUBP1 mutations have been found to occur in approximately 15% to 20% of oligodendrogliomas in three studies." (PMID 23527265, 2013). "Approximately 70% of oligodendrogliomas harbor CIC mutations, which may be associated with poor patient outcomes." (PMID 40426960, 2025). "Of note, oligodendrogliomas display marked mutational heterogeneity with frequent occurrence of mutations of the genes for capicua transcriptional repressor (CIC) and telomerase reverse transcriptase (TERT) and even other mutations, but they are not sufficient for diagnosis." (PMID 36941392, 2023). "CIC gene mutations are discovered in 69% of oligodendrogliomas." (PMID 36290366, 2022). "Additionally, the capicua transcriptional repressor (CIC) gene on chromosome 19q has recently been extensively explored, where oligodendroglioma and oligoastrocytomas cooperate with the mutation of the CIC gene." (PMID 36290366, 2022). "CIC mutation was found in 65.9% of oligodendrogliomas and 2.32% of diffuse astrocytoma." (PMID 32676453, 2020). "Other studies have confirmed the very frequent occurrence of CIC mutations in oligodendrogliomas." (PMID 30279357, 2018). "The higher rate of CIC mutations in pure oligodendrogliomas suggests CIC mutations may be related to the phenotypic characteristics of these tumors." (PMID 25943885, 2015). "However, it must be stressed that the CIC gene on chromosome 19q has been recently found to be mutated in the majority of 1p/19q codeleted oligodendrogliomas, suggesting that it may be a potential TSG in this region." (PMID 24083241, 2013). "In oligodendroglioma, telomerase reverse transcriptase (TERT) promoter mutations are characteristic and capicua transcriptional repressor (CIC) and Far Upstream Element [FUSE] Binding Protein 1 (FUBP1) alterations are also enriched." (PMID 39899075, 2025). "Recurrent molecular genetic alterations, such as IDH1/2, FUBP1, CIC, and TERT promoter mutations, have been identified to co-occur with 1p/19q co-deletion in oligodendrogliomas." (PMID 40426960, 2025). "In contrast to CIC mutations, IDH mutations are highly monomorphic and disease-defining in astrocytomas and oligodendrogliomas." (PMID 36303101, 2022). "LGGs with an IDH1 mutation and 1p19q co-deletion show oligodendroglioma histological characteristics and arise from TERT activation, mutations in CIC and FUBP1, and activating alterations in the phosphoinositide-3-kinase (PI3K) pathway." (PMID 32120790, 2020). "Further molecular studies identified mutations in TERT (telomerase reverse transcriptase), FUBP1 (far upstream element-binding protein 1), and CIC (capicua transcriptional repressor) in oligodendrogliomas." (PMID 32444979, 2020). "All of the oligodendroglioma tumor samples shared driver-like mutations in IDH1, TERTp, CIC, and FUBP1." (PMID 32904945, 2020). "Since loss-of-function mutations in CIC occur in a subset of IDH-mutant, 1p19q co-deleted oligodendrogliomas, we examined genes that were differentially expressed in CIC mutant versus CIC wild-type tumors using TCGA oligodendroglioma data." (PMID 30737375, 2019). "Astrocyte subpopulation gene signatures (PopD, PopE, Cortex, and PopA cortex) clustered a subset of LGG samples into oligodendrogliomas with IDH mutation and 1p/19q codeletion, TERT promoter mutations, and CIC gene mutations." (PMID 30957015, 2019). "Of the genes already associated with the development of oligodendroglioma (IDH1/IDH2, CIC, and FUBP1), remarkably only the mutation in IDH1 (NM_005896:c.395G>A) was present in the primary O2005." (PMID 31217899, 2019).
oligodendroglioma (continued). "CIC and FUBP1 mutations are frequently mutated in IDH mutated 1p/19q-codeleted oligodendroglioma and the prognostic impact has been investigated in several series." (PMID 29663171, 2018). "Frequently occurring driver mutations in oligodendrogliomas include mutations in IDH1, CIC, FUBP1, TERT promoter and NOTCH." (PMID 25694352, 2015). "CIC, the human homolog of Drosophila Cic, has been implicated in several human diseases including spinocerebellar ataxia type 1 (SCA1) neuropathology, oligodendroglioma (OD) and Ewing-like sarcoma." (PMID 26683696, 2015). "We next measured ACLY and pACLY levels in 1p19q co-deleted oligodendroglioma patient samples with known CIC and IDH1 status." (PMID 25277207, 2014). "We have successfully established and serially passaged a grade III oligodendroglioma xenograft with the hallmark chromosome 1p and 19q losses and mutations including FUBP1, CIC, and IDH1 (R132H)." (PMID 23527265, 2013). "CIC and FUBP1 mutations occurred frequently in oligodendrogliomas (46% and 24%, respectively) but rarely in astrocytomas or oligoastrocytomas (<10%)." (PMID 22869205, 2012). "Our patient’s tumor harbored mutations in TERT, FUBP1, and CIC, which are common alterations in oligodendroglioma, but not clinically relevant." (PMID 39857783, 2025). "Notably, in patients with grade 2 oligodendroglioma harboring IDH mutation, 1p/19q co-deletion, and CIC mutation, the administration of PCV chemotherapy following radiotherapy has demonstrated significant survival benefits." (PMID 40426960, 2025). "Therefore, a more biologically informative and clinically relevant oligodendroglioma model would be introducing the 1p/19q co-deletion and other coordinating mutations (eg, TERT promoter, and FUBP1 or CIC) in IDH mutant cells of the oligodendrocytic lineage." (PMID 36225650, 2022). "The role of CIC point mutations in oligodendroglioma development and progression has not been experimentally verified." (PMID 32238859, 2020). "In addition, in oligodendroglioma (IDH mutation and 1p/19q codeletion) patients, CIC mutation is associated with a better prognosis (p = 0.0362)." (PMID 32676453, 2020). "Moreover, mutations of homolog of Drosophila capicua transcriptional repressor (CIC) and far upstream element binding protein 1 (FUBP1) occur frequently in tumors with 1p/19q loss in oligodendrogliomas." (PMID 32825279, 2020). "So far, no study has investigated associations between CIC mutation status and MR imaging features in oligodendroglial tumours." (PMID 31215432, 2019). "To date, although several studies have evaluated MRI characteristics as they relate to IDH/1p19q status, no study has investigated associations between CIC mutation status and MR imaging features in oligodendroglial tumours." (PMID 31215432, 2019). "In IDH mutated 1p/19q-codeleted oligodendroglioma, both CIC and FUBP1 mutations were frequent events, but neither was associated with prognosis." (PMID 29663171, 2018). "In addition, FUBP1 has been shown to be associated with poor prognosis in glioma patients, and mutations in CIC and FUBP1 have been reported to contribute to human oligodendroglioma." (PMID 29371945, 2017). "The 1p deletion did not include FUBP1 but the region of loss on 19q did include CIC, both oligodendroglioma-implicated genes." (PMID 27028405, 2016).
oligodendroglioma (continued). "Another study characterizing CIC mutations hypothesized that because CIC mutations were highly associated with IDH mutation, the hemizygous presentation of mutant CIC may be correlated with oligodendroglioma pathogenesis in IDH mutants." (PMID 40564017, 2025). "A majority of oncogenic driver-related genetic alterations were observed in CIC-mutant tumors in GBM, astrocytoma, and oligodendroglioma." (PMID 37291277, 2023). "The gene set includes IDH1, IDH2, BRAF, CDKN2A/B, PTEN, and NOTCH1, but misses CIC, FUBP1, ATRX, and H3-3A important for oligodendroglioma and astrocytoma diagnosis." (PMID 37908227, 2023). "This study also confirmed previous reports by our team and others identifying CIC and FUBP1 as potential oligodendroglioma tumor suppressor genes lost on chromosomes 1p and 19q, respectively." (PMID 35957904, 2022). "Recent exomic sequencing of oligodendrogliomas revealed inactivating mutations in two tumor suppressor genes: homolog of Drosophila capicua (CIC) and far-upstream binding protein 1 (FUBP1) in 53% and 15% of oligodendrogliomas, respectively." (PMID 22869205, 2012). "Among IDH1/2-mutant gliomas, TERTp (38.8%), CIC (24.3%), and FUBP1 (15.3%) alterations exhibited a subtype-specific distribution, with CIC/FUBP1 mutations predominant in oligodendrogliomas (62.0%/39.2%) and rare (<2%) in non-oligodendroglial subtypes." (PMID 41377022, 2025). "Some tumors with 1p/19q co‐deletion are accompanied by mutations in CIC and FUBP1, but these mutations do not seem essential for the establishment of the histological and clinical features of oligodendroglioma." (PMID 37533228, 2023). "The alterations in FGFR4, KIT, and PEG3 were correlated with a short OS in astrocytoma, alterations in CDK4, FUBP1, and NTRK2 were correlated with a short OS in oligodendroglioma, and alterations in CDK4, CIC, FGFR3, and KMT5B were correlated with a short OS in glioblastoma." (PMID 36998447, 2023). "However, it misses oligodendroglioma important pathogenic variants in p-TERT, CIC, FUBP, and NOTCH1." (PMID 37908227, 2023). "RNAseq data from TCGA identified 221 differentially expressed genes in CIC mutant versus wild-type oligodendrogliomas (fold cutoff of 1.5, p-value < 0.05 and FDR < 10%) amongst which the known CIC targets ETV1, ETV4, and ETV5 were significantly up-regulated in CIC-mutant cases." (PMID 30737375, 2019). "In addition, situations such as Sample 18 and 19, which appeared to be oligodendrogliomas, may demonstrate how FUBP1 and CIC mutations and histopathological features without the hTERT promoter mutation could potentially predict the presence of 1p19q codeletion." (PMID 32118206, 2020).